RET (ret proto-oncogene)
Diseases named in the same sentence as RET in open-access papers (continued):
Sharing a sentence is not in itself a finding about the gene and the disease.
tumor (continued). "Differences in tumour histopathology between RET and DMBA exposure imply distinct underlying mechanisms of carcinogenesis, potentially involving variations in oncogenic pathway activation, cellular receptor interactions or the ability to induce inflammation and tissue remodelling." (PMID 40211435, 2025). "This might reflect a common origin from neural crest cells associated with the multidirectional differentiation of tumor cells driven by RET mutation, presenting a unique molecular pathogenic mechanism of ECS." (PMID 41306433, 2025). "The RET proto-oncogene encodes a cell membrane receptor tyrosine kinase, and when altered, it can lead to the activation of oncogenic signaling pathways that drive tumor formation." (PMID 40507982, 2025). "Tumour tissue harboured a somatic pathogenic RET variant p.(M918T) and selpercatinib was commenced." (PMID 38804700, 2024). "Clinicians may also test for Neurotrophic Receptor Tyrosine Kinase (NTRK) fusions, microsatellite instability-high/deficient mismatch repair biomarkers, tumor mutational burden, and Ret Proto-Oncogene (RET)-fusion in certain circumstances." (PMID 38542380, 2024). "The identification not only of RET mutations in tumor tissue, but also of predictive indicators for the efficacy of PRRT, for example CCK2R and SSTR2 imaging, will likely be of great importance for the choice of the most appropriate therapy of MTC on an individual level." (PMID 38581480, 2024). "In this study, we reasoned that Δψm-inducing effects of vandetanib and cabozantinib are due to RET inhibition and hypothesized that a low dose of selpercatinib will also increase Δψm in RET-mutated tumor cells, priming the tumor cells to MitoQ sensitivity." (PMID 38378752, 2024). "Oncogenic activating RET mutations are drivers of proliferation and tumor growth in PCC." (PMID 38687678, 2024). "In MTC, various RET mutation sites are not only associated with tumor invasiveness but also serve as decisive indicators for whether or not to perform a prophylactic thyroidectomy." (PMID 39235852, 2024). "In accordance with the tumor-agnostic philosophy, however, mutated RET variants were also found in neoplasms of breast tissue, widening the diagnostic and treatment repertoire for HER2-negative and -positive breast cancers which are resistant to current traditional treatment." (PMID 38920700, 2024). "We posit that selpercatinib preferentially sensitize RET-mutated tumor cells to MitoQ, proposing that our strategy to combine selpercatinib and MitoQ might confer an advantage in therapeutically using the agent." (PMID 38378752, 2024). "Analysis of original tumors and metastases showed that about 80% of sporadic cases of MTC included at least 1 subpopulation of cancerous cells with mutations in codon 918 in the protooncogene RET, and the frequency of this mutation depended on the tumor region." (PMID 39767735, 2024). "In two patients with BIF5B-RET or CCDC6-RET + NSCLCs treated with selpercatinib, acquired heterogenous front solvent G810X (G810R, G810S, and G810C at different tumor sites) RET mutations were documented, which can sterically inhibit the binding of selpercatinib to RET fusions." (PMID 39199650, 2024). "Path/LP variants in RET were identified in 5 participants with different tumor types." (PMID 37966258, 2023). "In addition, RET fusion-positive NSCLC patients have an inadequate response to immunotherapy due to low tumor mutation load and low programmed cell death ligand 1 (PD-L1) expression." (PMID 37603207, 2023). "The cumulative results of predictors and structural protein indicate that selected tumor-associated PTPRS mutation is a strong candidate to be associated with the development of non-RET MTC, but mutational screening of this gene in these familial cases should be clarified." (PMID 37175550, 2023).
tumor (continued). "Finally, in sporadic MTCs, RET mutation was found to be an indicator of poor prognosis, with an increased risk of both tumour recurrence (OR = 3.01, 95%CI [1.65–5.48], I2 = 41%) and patient death (OR = 2.43, 95%CI [1.06–5.57], I2 = 33%)." (PMID 37835559, 2023). "Other authors have reported atypical cases of late onset MEN2-related tumours despite carrying the high-risk RET variant C634, highlighting that other factors might modify the natural history of MEN2-related MTC." (PMID 37835559, 2023). "The presence of RET mutations, both together and when considering M918T alone, correlates to an advanced stage of the disease (p = 0.0025), a higher tumour (T) category (p < 0.0001), and the presence of both lymph-node (N) (p = 0.0021) and distant metastases (M) (p = 0.0073)." (PMID 37835559, 2023). "Finally, RET-rearranged patients typically exhibit low levels of PD-L1 expression and a low tumor mutational burden, and they tend to have unfavorable outcomes when treated with immunotherapies." (PMID 38132167, 2023). "RET alterations, such as fusions or mutations, drive the growth of multiple tumor types." (PMID 37627175, 2023). "In addition, tumor mutational burden (TMB) was significantly lower when compared to RET wild-type cancers (1.75 vs. 5.27 mutations/megabase, respectively), reflecting the presence of an oncogenic driver." (PMID 37627175, 2023). "Similarly to sunitinib, cabozantinib inhibits the tyrosine kinase enzymatic activities of multiple receptors including VEGFR2, MET, AXL, and RET, which have been implicated in tumor proliferation, survival and neoangiogenesis." (PMID 37752423, 2023). "In addition, treatment with MKIs were associated with emergence of mutations in the RET V804 gatekeeper residue, leading to acquired resistance and tumor escape." (PMID 38201460, 2023). "Furthermore, among such 15 synonymous mutation of SDHB gene, 9 tumor had RET gene mutation: exon 11, c.1901G > T, p.Cys634Phe (rs75996173): exon 11, c.2071G > A, p.Gly691Ser (rs1799939): or exon 11, c.1925 T > C, p.Val642Ala (rs766962871)." (PMID 35300626, 2022). "For tumours in which the RET mutation is detected, the basalCT values will be stricter." (PMID 35089388, 2022). "Indeed, RET mutations were found to be most associated with the prevalence of different tissues in the tumor microenvironment, with bronchi and vessels identified as the most impactful tissues, followed by mixed, stroma, lung, immune and necrosis." (PMID 36131239, 2022). "In addition to oncogenic fusions, germline mutations, such as activating point mutations, in RET are also associated with neoplasia and tumorigenesis, namely in multiple endocrine neoplasia type 2 (MEN2; described in 4.2)." (PMID 35957881, 2022). "It is worth highlighting that the transcriptome of RET-expressing lactating glands shares genes identified in post-partum breast tissue collected during the first 5 year period, a time frame in which there is an increased tumor risk." (PMID 35044452, 2022). "Interestingly, inhibition of RET in zebrafish tumor tissue was associated with a rebound of AKT pathway activation, in contrast to TPC1 cells, in which the AKT pathway remains suppressed after treatment with a selective RET inhibitor." (PMID 35510953, 2022). "HM06, another investigational compound, selectively inhibits RET across multiple tumor types in vitro and in vivo, circumvents RET-V804X gatekeeper mutation and RET-G810X resistance mutations, and is currently in Phase I/II clinical trials in patients with RET-altered tumors (NCT04683250)." (PMID 35957881, 2022). "Retrospective analysis revealed a somatic RET M918T mutation in the tumour tissue." (PMID 34659114, 2021). "Finally, RET fusions have been related to a low response to immune checkpoint inhibitors due to a low TMB (tumour mutational burden) as well as a low level of PD-L1 expression." (PMID 34503226, 2021).
tumor (continued). "Furthermore, there were two genes (FBXW7, RET) mutated exclusively in tumours and eight (BLM, GJB2, NOTCH2, NOTCH3, NTRK1, POLE, SOS1, TSC2) solely in metastases." (PMID 34572946, 2021). "Oncogenic RET mutations in patients with MTC is the main feature of tumor growth." (PMID 34207842, 2021). "The RET A919P variant along with the inclusion of a downstream pathway member such as the KIAA1549-BRAF fusion (identified in this tumour) may have an amplificative effect on the MAPK pathway." (PMID 34493325, 2021). "Thus, miR-129-5p tumor suppressor activity was potentially linked to reduced RET expression and AKT phosphorylation suppression." (PMID 33924120, 2021). "Similarly, the repression of COMETT markedly reduces the viability and proliferation of tumor cells harboring BRAF mutation or RET oncogene rearrangement, as well as the motility and invasiveness of tumor cells in vitro." (PMID 33142861, 2020). "MD Anderson Group demonstrated that circulating RET M918T cell-free DNA (cfDNA) could be detected in about 1/3 of sporadic MTC patients with elevated serum Ct level (>100 pg/mL) and advanced disease stages, harboring RET M918T mutation in tumor cells." (PMID 33112827, 2020). "Patients diagnosed with NSCLCs with RET rearrangements were analyzed for concomitant mutations, tumor mutation burden (TMB), PD-L1 expression, T cell receptor repertoire and clinical outcomes with chemotherapy, immune checkpoint inhibitors (ICIs), and multikinase inhibitors (MKIs)." (PMID 32295619, 2020). "Approximately 50% of them harbor somatic RET mutations in tumor cells." (PMID 33112827, 2020). "Similarly, in the same population, a statistically significant association between RET mutations and male gender, tumor size, lymph node and distant metastases, advanced disease, increased risk of persistent disease, and poorer overall survival was observed." (PMID 33112827, 2020). "Although in the present study, a RET mutation could only be proven in a minority of the cases (3/8, 37.5%), these different oncogenic mechanisms underscore the complexity of tumor biology in progressive MTC." (PMID 30206772, 2019). "Recent works have suggested that MEN 2-associated tumors may require a second hit in the RET gene to initiate tumorigenesis, similar to that seen for tumor suppressor genes." (PMID 31288802, 2019). "Importantly, RET is implicated in promoting tumor-related inflammation, the infiltration of immune cells into the tumor environment, a key indicator of disease outcomes and therapeutic responses." (PMID 30666215, 2018). "Interestingly, recent studies have also linked RET to alterations in tumor metabolism, an emerging hallmark of cancer, through a novel ligand complex involving Growth Differentiation Factor 15 (GDF15) and the GDNF Family Receptor α-like (GFRAL)." (PMID 30666215, 2018). "It is conceivable that a few cells in the primary tumor were positive for the mutations found in the lymphnodes which received a growth advantage during the selective pressures of the metastatic process and produced RET-positive metastases." (PMID 29515777, 2018). "Moreover, tumor samples harbouring RET mutations showed positivity for phospho-Y905 and phospho-Y1062 residues while the normal mucosa samples were either negative or presented weak positivity." (PMID 29665843, 2018). "Patient with catecholamine-secreting tumours due to RET and NF1 mutations secrete high levels of metanephrine, indicating epinephrine production in the tumour, while patients with mutations in the VHL gene exhibited an increased production of normetanephrine, indicating norepinephrine production." (PMID 29166454, 2017). "Tenascin C correlates significantly with tumor proliferation, especially in RET-mutated tumors." (PMID 27409604, 2016).
tumor (continued). "Specifically, Clusters C1A and C1B, comprising SDHx- and VHL-mutated tumours, respectively, display a pseudohypoxic signature, whereas Cluster C2A, corresponding to RET-, NF1- and TMEM127-mutated tumours, displays activation of the RAS/mitogen-activated protein kinase (MAPK) signaling pathway." (PMID 25625332, 2015). "Consistent with this hypothesis, our data in the present study has demonstrated that tumours with the BRAFV600E mutation were significantly smaller than BRAFV600E-negative cases including RET/PTC or ETV6/NTRK3." (PMID 26584635, 2015). "C2A tumours are mainly driven by RET, NF1 and HRAS mutations." (PMID 25625332, 2015). "Additionally, the catecholamine output observed in H-RAS mutated tumours resemble that of RET and NF1." (PMID 24466223, 2014). "Caspase-3 cleavage and PARP-1 activation demonstrate that siRNA RET/PTC3 might cause DNA damage which activates the cell death machinery for the destruction of tumour cells." (PMID 24759995, 2014). "There is limited evidence that polymorphisms in RET or in other components of the RET signaling system, such as GFR alpha-1, may influence the age of onset of a RET mutation associated tumor phenotype or have a traceable modifier effect on disease expression." (PMID 23455356, 2013). "The contribution to tumour development of somatic RET mutations in MTC pathogenesis is unclear." (PMID 22654561, 2011). "Somatic RET mutations can be detected in tumour tissue of 40-60% of sporadic MTC patients." (PMID 22654561, 2011). "RET-positive tumours seem to be associated to a worse clinical outcome." (PMID 19401695, 2009). "In contrast to this theory, Volante proposed that the components of the two carcinomas are not derived from a single progenitor cell, because they observed different patterns of RET proto-oncogene mutation, loss of heterozygosis and X-chromosomal inactivation in a lot of these tumours." (PMID 17997826, 2007). "Indeed, the majority of these lymphocytic DNAs (6/7 samples) showed a heterozygous G691S RET variant sequence (A1/A2), suggesting a probable loss of the wild type allele A1 in the tumour samples." (PMID 12085189, 2002). "Interestingly, tumors with RET mutations tend to exhibit a higher sensitivity to regimens that include pemetrexed chemotherapy, possibly due to lower expression levels of thymidylate synthase in RET-mutated tumor tissues." (PMID 40083325, 2025). "However, mutations or fusions in RET can result in abnormal proteins, which can fuel uncontrolled cell growth, prevent programmed cell death, and stimulate the growth of new blood vessels feeding the tumor." (PMID 39086985, 2024). "RET alterations, including mutations, rearrangements, and amplifications, result in ligand‐independent constitutive activation of intracellular tyrosine kinases and downstream signaling pathway transmission, which subsequently promote tumor cell proliferation and invasion." (PMID 38349001, 2024). "Furthermore, it has been suggested that changes in the tumor microenvironment caused by prior VEGF-targeted therapies may result in resistance to RET inhibitors." (PMID 38647958, 2024). "Validation of the in vitro and in vivo findings reviewed above using patient tumor samples and publicly available datasets suggests that both RET and GFL ligand expression are linked with endocrine resistance, but that ligand availability may be a crucial limiting factor." (PMID 36918928, 2023). "However, the solid-patterned tumor loci may be driven by other oncogenes, e.g., RET/PTC3 fusion, which, in turn, is associated with the most aggressive behavior of the diffuse sclerosing variant PTC." (PMID 35665338, 2022). "The tumor stages were unknown, and this might explain the low mutation rate of RET in that study." (PMID 34741450, 2021).
tumor (continued). "Importantly, immunoblot detected very low RET expression in LuCaP 173.1 tumors but we used a RET primary antibody that cross-reacts with mouse RET and the observed RET protein expression is likely derived from murine immune cells associated with the tumor microenvironment." (PMID 33471819, 2021). "However, mutations causing increased activity of RET functions can result in tumor formation." (PMID 34832869, 2021). "Furthermore, elevated RET expression is observed in ALK-mutated primary NB tumor samples." (PMID 33921066, 2021). "In addition to oncogenic mutations, increased expression or activity of wildtype RET is now being recognized in many additional tumor types where it may have a range of different implications." (PMID 30666215, 2018). "Taking into account these and our present data, we suggest that the higher frequency of CCH observed in the irradiated thyroid glands of the patients bearing in their tumours a G691S RET SNP, may be an effect of the RET allele (or haplotype) on which the sequence variant has occurred." (PMID 12085189, 2002). "Broader testing to identify the eligibility for tumor-agnostic therapy for a tumor mutation burden (TMB), NTRK gene fusions, and RET fusions is encouraged for all patients with advanced solid tumors." (PMID 41899608, 2026). "In ALK-negative tumours, alternative drivers have been identified, including ROS1, RET, NTRK3 and PDGFRB rearrangements or mutations." (PMID 40980125, 2025). "This updated data further demonstrates the vast anti-tumor activity against RET-positive tumors and further provides hope in impacting the lives of patients with several types of solid-organ, metastatic, RET-positive cancers." (PMID 41179283, 2025). "We also used Sanger sequencing to detect six genes—KRAS, NRAS, HRAS, TERT, RET, and BRAF—in the tumor tissue and identified a C228T mutation in the TERT promoter region." (PMID 41488090, 2025). "As a multi-kinase angiogenesis inhibitor, sorafenib functions through the dual inhibition of Raf kinase signaling and receptor tyrosine kinase (RTK) autophosphorylation (VEGFR, PDGFR, c-Kit, RET), thereby suppressing tumor progression and vascular development." (PMID 40299340, 2025). "Receptor tyrosine kinase (RTK) inhibitors have been approved for the treatment of NTRK fusion (NTRK+) and RET fusion (RET+) positive solid tumors in a tumor‐agnostic manner." (PMID 39950716, 2025). "SY5007 has shown promising results, with a 62% response rate and a 94% disease control rate in RET-altered tumours, including MTC." (PMID 40332222, 2025). "A multi-institutional analysis of repeat tumor or plasma biopsies from patients with RET fusion-positive NSCLC treated with selpercatinib and pralsetinib identified the emergence of MET amplification (15%) and KRAS amplification in one case each." (PMID 39850629, 2025). "We aim to discuss the potential causes of ECS, evaluate the effectiveness of tumor debulking, steroidogenesis inhibitors, tyrosine kinase inhibitors (TKIs), bilateral adrenalectomy (BLA), and a new selective RET inhibitor in treating MEN 2-related MTC and ECS." (PMID 41306433, 2025). "A sestamibi (MIBI) scan was suspicious of a right-sided parathyroid adenoma, while genetic testing confirmed heterozygosity for a pathogenic RET variant, conferring risk of developing other MEN2-related tumours." (PMID 39555152, 2025). "The kinase signaling cluster (Cluster‐2) is associated with genes such as RET and NF1, which are related to higher tumor differentiation, lower malignant potential, and better prognosis." (PMID 40196048, 2025). "Mutations in RET activate key oncogenic pathways, including PI3K/AKT, RAS/RAF/MAPK, and PLCγ, driving tumor proliferation and growth." (PMID 40363930, 2025). "A total of 26 tumor tissues collected from RET-fusion positive NSCLC patients were performed targeted exome sequencing by the same panel covering 1021 genes." (PMID 40016191, 2025).